HMGN2 (high mobility group nucleosomal binding domain 2)
Diseases named in the same sentence as HMGN2 in open-access papers (continued):
Sharing a sentence is not in itself a finding about the gene and the disease.
tumor (18 papers, 2011 to 2026). "HMGN1 and HMGN2 affect DNA damage repair and organ development and maturation by regulating the expression of genes or proteins, and are also implicated in tumor immune responses." (PMID 36568211, 2022). "The expressions of HSP90B1, USP34 and HMGN2 were significantly negatively associated with tumour grade (p<0.001)." (PMID 22363530, 2012). "Overall, HMGN2 knockdown caused a significant change in tumor size and survival time in vivo." (PMID 40092489, 2025). "As expected, HMGN2 knockdown significantly reduced tumor size compared with the NC group and the scrambled group." (PMID 40092489, 2025). "The importance of HMGN2 in embryonic development, lineage characterization and maintenance, controlling of cell type-specific gene expression, and tumor progression and inhibition has drawn our attention." (PMID 40092489, 2025). "Preliminary results indicate that HMGN2 promotes tumor cell progression by regulating the cell cycle." (PMID 40092489, 2025). "As a member of the HMGN family, HMGN2 is a key regulator of transcriptional activation in gene expression and has been shown to significantly inhibit tumor cell proliferation, migration, and angiogenesis, exerting anti-tumor effects." (PMID 40406620, 2025). "HMGN2 protein not only is expressed in tumor cell lines but also work as an anti-tumor effector molecular released by CD8+ T cells." (PMID 38225273, 2024). "show that the nucleosome-binding domain F3 peptide of HMGN2 is a promising potential tumor therapeutic target, suggesting unique prospects for drug-targeting applications because it can be absorbed by cells and carry payloads to the nucleus." (PMID 36568211, 2022). "HMGN2 is also reported as potential tumor suppressor and plays an important role in DNA damage response." (PMID 33251127, 2020). "PBMCs and CD8+ T cells were then activated by PHA or tumor antigen, followed by analysis of HMGN2 protein expression and release." (PMID 25060707, 2014). "H&E staining indicated that necrosis occurred in the majority of the HMGN2-treated xenografts during tumor formation." (PMID 24348831, 2014). "A 50% reduction in average tumor volume was observed in HMGN2-treated tumors compared with controls." (PMID 24348831, 2014). "In order to ensure that HMGN2 was an effector protein of tumor antigen activated T cells, we used tumor full protein as tumor antigen (T-Ag) to stimulate PBMCs for 7 days." (PMID 25060707, 2014). "Our results showed that activated CD8+ T cells express high levels of HMGN2 protein, and HMGN2 protein in the culture supernatant of activated CD8+ T cells had proved had anti-tumor effect." (PMID 25060707, 2014). "F3 peptide (KDEPQRRSARLSAKPAPPKPEPKPKKAPAKK), a 31 amino acid fragment of HMGN2 protein identified by Ruoslahti's group using in vivo phage display techniques, has been shown to bind to tumor and endothelial cells in tumor blood vessels." (PMID 21811604, 2011). "The expression of HMGN2 correlates with Th2 cells and T helper cells, suggesting that it may play a role in tumor immune escape." (PMID 40092489, 2025). "In the KEGG enrichment analysis, the “cell cycle” pathway was enriched with the most DEGs, indicating that “cell cycle” regulation may be involved in the impact of HMGN2 on tumor pathogenesis (P < 0.001)." (PMID 40092489, 2025). "Fluorescence-labeling assays showed that HMGN2 in the supernatant of activated CD8+ T cells could be significantly transported into tumor cells." (PMID 25060707, 2014). "The supernatant was able to kill tumor cells in a dose-dependent manner; 20% supernatant could significantly kill tumor cells, as could the HMGN2 positive control." (PMID 25060707, 2014). "Tumor antigen-activated CD8+ T cells also released high levels of HMGN2." (PMID 25060707, 2014). "To confirm that the HMGN2 in the supernatant of T-Ag activated CD8+ T cells could be transmembrane transported into tumor cells, we used fluorescence FITC to label the proteins in the supernatant, before adding to the medium." (PMID 25060707, 2014).
tumor (continued). "The HMGN2 gene is highly conserved and is located near several tumor suppressor genes." (PMID 24348831, 2014). "Fluorescence-labeling assays showed that the supernatant proteins of activated CD8+ T cells could be transported into tumor cells, and the transport visibly decreased after HMGN2 was depleted by anti-HMGN2 antibody." (PMID 25060707, 2014). "A tumor formation assay was performed to determine whether HMGN2 is able to affect the growth of Tca8113 cells in vivo." (PMID 24348831, 2014). "Our results suggest that HMGN2 is an anti-tumor effector molecule of CD8+ T cells." (PMID 25060707, 2014). "The effect of killing tumor cells by the supernatant could be significantly inhibited by the anti-HMGN2 antibody." (PMID 25060707, 2014). "In addition, the supernatants of activated CD8+ T cells were able to kill tumor cells in a dose-dependent manner, and the tumor-killing effect of the supernatant could be significantly inhibited by anti-HMGN2 antibody." (PMID 25060707, 2014). "In the tumor lesion, a malignant STMN1+HMGN2+GPC3+ cell subtype enriched in MVI+ HCC was identified, which exhibited enhanced proliferative activity and was associated with poor prognosis." (PMID 42139279, 2026). "Both HMGN2 and MED1 are reported as potential tumor suppressors and are known to play an important role in DNA damage response." (PMID 33251127, 2020). "HMGN2 and MED1 have been previously reported as potential tumor suppressors and are known to play important role in DNA damage response." (PMID 33251127, 2020). "In addition, we found the same lineage-defining genes of the murine trajectory (DBI, HMGN2, STMN2) selectively expressed among the human tumor cells." (PMID 40562749, 2025). "Immunohistochemical labeling of HMGN2 in primary ESCC tumor tissue sections (from smokers) showed no detectable expression while strong to moderate staining of HMGN2 was observed in normal esophageal tissues." (PMID 33251127, 2020). "Our previous research has shown that high mobility group nucleosomal-binding domain 2 (HMGN2) could be released by IL-2 and PHA stimulated peripheral blood mononuclear cells (PBMCs) and also induced tumor cells apoptosis at low doses." (PMID 25060707, 2014). "Non-histone chromosomal protein HMG-17 (HMGN2), thymosin beta-4 (TMSB4X), 10 kDa heat shock protein (HSPE1), and the ratio between citrullinated/uncitrullinated GFAP fragment 388–432 showed significantly higher levels in ST-EPs, therefore marking the ST tumor location." (PMID 32183175, 2020).
infection (3 papers, 2016 to 2025). The state of being infected such as from the introduction of a foreign agent such as serum, vaccine, antigenic substance or organism. "The right panel shows the cellular changes in the state of HMGN2-deficiency: under the same infection conditions, histone modification in the CD14 gene promoter region of macrophages is altered, promoting the upregulation of CD14 expression." (PMID 41246296, 2025). "Nevertheless, the function of HMGN2 in macrophages during infection and the associated regulatory mechanism remain ambiguous." (PMID 41246296, 2025). "Ma.24 infection caused the down‐regulation of IL‐10 which was further decreased by HMGN2 knock‐down in macrophages, while we observed that there is no obvious influence by Ma.24 infection and HMGN2 knock‐down on TGF‐β expression in macrophage." (PMID 31596045, 2019). "Concerning potential mechanisms for dynamically regulating HMGN2 during the period of infection, our review of literature reveals that HMGN2 expression has been primarily found to be regulated by microRNAs." (PMID 41246296, 2025). "A reduction in HMGN2 expression in macrophages during the infection process can enhance phagocytic activity and bacterial clearance by facilitating Cluster of differentiation 14 (CD14)-mediated nitric oxide (NO) release." (PMID 41246296, 2025). "HMGN2 expression in macrophages was also elevated at 3, 6, and 12 hours post-infection with Mycobacterium tuberculosis." (PMID 41246296, 2025). "With using the NO production assay, we measured that the enhanced production of NO in HMGN2 silenced RAW264.7 was at 12 hours after infection, while HMGN2 silenced MH‐S displayed the increasing of NO production at 6 hours." (PMID 31596045, 2019). "In the current study, we firstly investigated the macrophage polarization potential upon the two strains of non‐tuberculous mycobacteria infection, and then we show the expression pattern of HMGN2 in macrophages under different infection conditions." (PMID 31596045, 2019). "Strikingly, the modulation of HMGN2 by miR-155 displayed an infection-dependent manner as our result showed the cellular level of HMGN2 responded to miR-155 mimic or inhibitor specifically during K. pneumoniae infection compared with un-infected group." (PMID 27534887, 2016). "Clinically, HMGN2 and its downstream molecules may serve as novel biomarkers for infection diagnosis, disease monitoring, and prognosis assessment." (PMID 41246296, 2025). "HMGN2 knockout had stronger bacteria-eliminating capacity than WT, showing HMGN2 still regulates macrophage antibacterial efficiency at the relatively late stage of infection." (PMID 41246296, 2025). "Collectively, present study suggests an novel role of HMGN2 in anti‐NTM innate immunity, and HMGN2‐specific inhibition or interfering might thus represent a favourable approach for the treatment of NTM‐related infection." (PMID 31596045, 2019). "Herein, our data further suggest multiple mechanisms may participate in the miRNA-mediated and infection-dependent HMGN2-integrin-actin axis to regulate host cell autonomous immune response." (PMID 27534887, 2016). "More interestingly, HMGN2 protein level responded to miR-155 modulation only under infectious condition, suggesting an unknown infection-specific mechanism play potential roles in miR-155-mediated HMGN2 expression regulation." (PMID 27534887, 2016). "Therefore, we hypothesize that HMGN2 plays a role in the process of macrophage reprogramming by affecting the function of transcriptional regulatory elements at the chromatin level during infection." (PMID 41246296, 2025). "Therefore, we speculated that the HMGN2 may also play a role in macrophage antibacterial infection." (PMID 31596045, 2019).
bacterial infection (2 papers, 2019 to 2025). "We established a murine bacterial infection model to investigate the impact of HMGN2 knockout on the ability of mice to eliminate pathogenic microorganisms." (PMID 41246296, 2025). "In vivo, HMGN2 expression in mouse lung macrophages significantly reduced 24 hours after bacterial infection." (PMID 41246296, 2025). "This study reveals that during bacterial infection, the decrease in HMGN2 levels precisely regulates the acetylation and methylation modifications of histone H3, driving a significant upregulation of CD14 gene transcription." (PMID 41246296, 2025). "To investigate the impact of bacterial infection on HMGN2 expression in macrophages, we stimulated the mouse RAW264.7 macrophage cell line with Escherichia coli (E. coli) endotoxin lipopolysaccharide (LPS)." (PMID 41246296, 2025). "In this study’s focus (after 24 hours, late LPS stimulation or bacterial infection), HMGN2 expression decreased and its immune response differed." (PMID 41246296, 2025). "In the current study, we verified that HMGN2 is indispensable for the immune response of macrophages during bacterial infection." (PMID 41246296, 2025). "HMGN2 has been shown as a quick responsive gene to bacterial infection in epithelial cell." (PMID 31596045, 2019). "For therapeutic applications, future research could develop small-molecule inhibitors, epigenetic regulatory drugs, or cellular gene-editing therapies based on HMGN2 to enhance innate immunity, which can be combined with antibiotics to tackle drug-resistant bacterial infections." (PMID 41246296, 2025).
infectious disease (1 paper, 2025). A disorder directly resulting from the presence and activity of a microbial, viral, or parasitic agent in humans. "Our findings indicate that HMGN2 holds significant potential as a therapeutic target for clinical infectious diseases." (PMID 41246296, 2025). "HMGN2 is anticipated to serve as a therapeutic target for the treatment of infectious diseases." (PMID 41246296, 2025).
HMGN2 also shares sentences with these, for which no sentence is quoted: cancer (4 papers); acute myeloid leukemia (1); allergic rhinitis (1); bladder cancer (1); breast tumors (1); colon cancer (1); ependymoma (1); glioblastoma (1); hepatoma (1); leukemia (1); lung adenocarcinoma (1); neuroblastoma (1); posterior fossa ependymoma (1); viral infection (1).